MTOR (mechanistic target of rapamycin kinase)
Diseases named in the same sentence as MTOR in open-access papers (continued):
Sharing a sentence is not in itself a finding about the gene and the disease.
tumor (continued). "The anti-tumor effects of the mTOR inhibitor WYE132 could be enhanced upon combination with avastin in lung and breast xenograft models." (PMID 23085539, 2012). "c-erb-B2, EGFR, mTOR, ERCC1 overexpression levels, and loss of p27 may play roles in hepatocarcinogenesis and may be significant predictors of aggressive tumor behavior." (PMID 23162604, 2012). "Overactivation of the PI3K-Akt-mTOR-p70S6K axis is common in many tumor types." (PMID 23056346, 2012). "In addition, We detected the expression of mTOR in tumor xenografts after miR-99a injection by Western blot, we found that intratumoral delivery of synthetic miR-99a makedly suppressed mTOR expression compared with control mice." (PMID 23173671, 2012). "The mTOR pathway was aberrantly activated in most OSCC tumours." (PMID 22333597, 2012). "mTOR inhibitors have radiosensitising potential in tumor and vascular cells." (PMID 22452803, 2012). "If autophagy induction by mTOR inhibitors promotes tumor cell survival, then combination treatment with an autophagy inhibitor may be expected to promote tumor cell death." (PMID 22848625, 2012). "Activation of PI3K signalling, through AKT activation, PTEN deletion, growth factor stimulation or aberrant growth factor receptor signalling, may indicate potential sensitivity of tumours to mTOR inhibition." (PMID 22408430, 2012). "Although there are distinctions between the effects of mTOR inhibitors and antiangiogenic agents on tumor vasculature, it was suggested that rapamycin induced antiangiogenic effects also mediate vascular re-normalization as in the case of conventional antiangiogenic agents." (PMID 23185335, 2012). "The results of this study demonstrate that PI3K/mTOR inhibitors can enhance radiation-induced killing in tumor and endothelial cells and may be of benefit when combined with radiotherapy." (PMID 22452803, 2012). "Consistently, mTOR phosphorylation was partially reduced and so was the activity of this key enzyme indicated by lower 4EBP1 phosphorylation that was more significant in A549 tumours." (PMID 22607554, 2012). "Interestingly, these negative regulators of mTOR, that is, TSC1, TSC2, and LKB1, are tumor suppressors, and germline mutations of TSC1/2 or LKB1 cause hamartomas and predisposition to multiple malignancies in humans." (PMID 22666248, 2012). "As well, the mechanisms of in-vivo anti-tumor effect by these drugs should be more clarified, as inhibition of mTOR might result in anti-angiogenic effect by suppressing HIF1-VEGF pathway." (PMID 22662154, 2012). "Activation of pathways of mTOR also may promote tumor growth and increase the activation of inflammatory cell pathways that may negatively impact the cardiovascular system." (PMID 22545721, 2012). "To further address this question we plan to test the effect of rapamycin on animals with established tumors (by measuring tumor growth) along with evaluating the functional status of mTOR and the ability of rapamycin to suppress it in tumors and normal tissues." (PMID 23123616, 2012). "Consequently, interference with this signaling cascade is widely used for current tumor therapeutic regimens, e.g. mTOR inhibitors are in clinical use for the treatment of renal cell carcinomas and mantle-cell lymphomas." (PMID 23056346, 2012). "Indeed, the mTOR inhibitor Palomid 529, significantly suppressed BRCA1-deficient tumor growth in mice through inhibition of both AKT and mTOR signaling." (PMID 26097796, 2012). "Therefore, activation of the mTOR pathway provides tumor cells with a growth advantage by promoting protein synthesis." (PMID 23173671, 2012). "There results suggest that the tumor suppressive role of miR-99a may be mediated partially through mTOR pathway regulation." (PMID 23173671, 2012). "The mammalian target of rapamycin (mTOR) is an evolutionary conserved Ser/Thr kinase, which could play a major role in the metabolic reprogramming of tumor cells." (PMID 21969829, 2012).
tumor (continued). "In particular: (a) the capacity of tumor cells to develop escape pathways during treatments with mTOR inhibitors may suggest that combined treatments with other drugs may prove beneficial." (PMID 23344019, 2012). "Remarkably, the phosphatidylinositol 3′-kinase/Akt/mTOR signaling pathway is commonly activated in GBM through constitutive activation of upstream receptor tyrosine kinases, such as EGFR, and/or loss of PTEN tumor suppressor function." (PMID 24212957, 2011). "Newer research suggests that deregulation of the mammalian target of rapamycin (mTOR) cell proliferation/survival pathway may play an important role in desmoid tumor biology especially when the APC/β-catenin pathway is disrupted." (PMID 24212949, 2011). "In particular, we found a novel androgen-dependent mRNA isoform derived from an alternative internal promoter within the TSC2 tumour suppressor gene, which is predicted to encode a protein lacking an interaction domain required for mTOR inhibition." (PMID 22194994, 2011). "mTOR inhibitors are immunosuppressants that target and inhibit mTOR, and thereby exert antiproliferative, antiangiogenetic and tumor-progression blocking capabilities that might serve preventing uncontrolled cholangiocyte cell proliferation." (PMID 22104015, 2011). "The metabolic activity and nutrient supply of the tumor cell might also be affected by GSI treatment since mammalian target of rapamycin (mTOR) and the glucose transporter Glut1 have been shown to be downstream of Notch signaling." (PMID 21533193, 2011). "By combining everolimus with panobinostat we elude possible tumor escape mechanisms in response to mTOR inhibition (increased AR transcriptional activity and expression of known onco-miRs), resulting in, at least with this combination, cytostatic anti-tumor activity." (PMID 22087262, 2011). "In contrast to CNIs, the mammalian target of rapamycin (mTOR) inhibitor rapamycin (RAPA) may have a completely opposite effect in terms of tumor development." (PMID 21886838, 2011). "In this context, our finding of upregulated p-Akt (Ser473) and p-mTOR (Ser2448) in patient 1's resistant tumor that emerged following IGF1R antibody therapy is consistent with a resistance mechanism that could be related to upregulation of TORC2." (PMID 21494688, 2011). "Gorlick, Houghton, and others have reported relative insensitivity to IGF-1R- or mTOR-targeted therapies in vitro compared to xenografts models of similar tumor types, supporting our hypothesis that extracellular mechanisms of resistance are important." (PMID 24212944, 2011). "LDH is a serum enzyme, which is regulated by the PI3K-Akt-mTOR pathway and tumour hypoxia." (PMID 22738081, 2011). "Intriguingly, inhibition of mTOR also promotes expansion of immunosuppressive regulatory T cells (Tregs) that can inhibit anti-tumor immune responses in a clinically relevant way in various tumor types including RCC." (PMID 22129044, 2011). "In addition, recent progress been made in targeting the ATP-binding site of mTOR with small molecule inhibitors that exhibit anti-tumour activity." (PMID 21649578, 2011). "The reduction in apoptosis may, in fact, reveal paradoxical effects of mTOR inhibitors on tumor progression." (PMID 21394210, 2011). "Moreover, despite the widespread belief that mTOR controls tumor growth and proliferation, clinical trials with mTOR inhibitors have been disappointing." (PMID 22190938, 2011). "Therefore, inhibition of mTOR has the potential to inhibit tumor progression at multiple levels, and along with PI3K inhibition is particularly attractive for development for RCC treatment." (PMID 21834980, 2011). "However, anti-tumor therapy with small molecule inhibitors against mTOR turned out to be less successful than expected." (PMID 22110663, 2011). "The PI3K/Akt/mTOR and MAPK signaling pathways are prone to mutations and aberrant activation in this tumor entity and might provide suitable targets for more effective therapies." (PMID 22110663, 2011).
tumor (continued). "Finally, rapamycin, an inhibitor of the mTOR pathway, greatly enhanced Notch-dependent inhibition of Akt and tumor cytoxicity in vitro." (PMID 22074495, 2011). "Rapamycin, an inhibitor of mTOR, can block tumor growth and inhibit tumor cell motility." (PMID 22145042, 2011). "Finally, it has also been reported that rapamycin-activated JNK signaling pathway in colon cancer cells plus combined JNK and mTOR inhibition had additive anti-tumor effects." (PMID 24212820, 2011). "However, higher pre-treatment eIF4E activity was significantly associated with dramatic post-treatment changes in expression of eIF4E and 4E-binding proteins, suggesting that eIF4E is further deregulated in these tumours in response to mTOR inhibition." (PMID 21320304, 2011). "The rationale for sequential therapy with mTOR inhibitors in rTKI refractory patients lies in the expectation that resistance of the tumor to rTKI treatment may be reversed by targeting a different signaling pathway." (PMID 21756335, 2011). "Evaluation of the expression status of both CAV1 and mTOR pathway components in these tumors may help to predict tumor response to novel pathway specific therapies, hence allowing appropriate selection of treatment for individual patients." (PMID 22152020, 2011). "Combinations of cytotoxic chemotherapeutic drugs and inhibitors which target the Raf/MEK/ERK, PI3K/PTEN/mTOR and upstream kinases may be an eventual approach to target the tumor microenviroment, however, specificity of targeting may be a significant problem." (PMID 21411864, 2011). "Inhibition of mTOR reduces secretion of VEGF by the tumor through inhibition of HIF-1α." (PMID 20072701, 2010). "There is also emerging evidence that mTOR activation may play a role in promoting cell survival through the activation of antiapoptotic proteins that contribute to tumor progression." (PMID 21584218, 2010). "Assessment of gene copy number variations in these tumours by CGH array showed gene copy number variations that could potentially lead to PI3K/Akt/mTOR pathway activation." (PMID 20664591, 2010). "Whether the paradoxical Akt activation secondary to mTOR inhibition led to the increased toxicity or rapid tumor progression in Study A cannot be stated with any degree of certainty as no post-treatment biopsies were performed." (PMID 20630061, 2010). "The possibility of blocking PDK1 and mTOR simultaneously in these tumours is likely to be very effective therefore, because of its dual inhibitory activity towards both enzymes, it would be interesting to investigate the effect of 2-O-Bn-InsP5 in these cellular contexts." (PMID 20051961, 2010). "This is important because the deregulation and activation of mTOR [mammalian target of rapamycin; official name: mechanistic target of rapamycin (serine/threonine kinase)] pathway may be behind of many tumor types." (PMID 20706540, 2010). "All of these agents have a putative anti-angiogenic mechanism of action whilst the mTOR inhibitors everolimus and temsirolimus may have direct anti-tumor effects in RCC." (PMID 20701793, 2010). "AKT phosphorylates TSC2 to inhibit its tumor suppressor function and activate mTOR signaling." (PMID 20169078, 2010). "mTOR is activated in 60–80% of gastric adenocarcinomas and is expressed in early-stage and advanced-stage disease, in both diffuse and intestinal subtypes, and in tumor cells that invade lymphatic channels." (PMID 21584218, 2010). "We found that mTOR or rictor deficient LS174T cells failed to form a tumor xenograft even after 60 days of observations." (PMID 20226010, 2010). "Whether overexpression of Akt or mTOR will render tumor cells resistant to CDDO-Me remains to be tested." (PMID 21799944, 2010). "However, by combining mTOR inhibition with an anti-androgen to block both the pathways from the beginning, tumour growth was statistically significantly reduced compared with the effect of these drugs alone in the LNCaP and HP-LNCaP xenografts." (PMID 20842117, 2010).
tumor (continued). "We next tested the effect of mTOR and rictor knockdown on tumor growth in vivo." (PMID 20226010, 2010). "In all cohorts modulation of the mTOR pathway in tumor and PBMC (pS6RP/S6RP) was demonstrated." (PMID 20543980, 2010). "Dysregulated PI3K/Akt/mTOR signaling has been documented in many types of neoplasias." (PMID 24281174, 2010). "In addition, Akt requires mTORC2 to achieve its full activation, suggesting that inhibition of mTORC2 is essential for preventing the progression of tumours with highly activated Akt/mTOR signalling." (PMID 19223902, 2009). "As mTORC1 complex is mainly found in the cytoplasm, tumours with cytoplasmic expression of mTOR may be more sensitive to mTOR inhibitors than those with nuclear expression of mTOR." (PMID 19223902, 2009). "Although researchers are actively studying mTOR inhibitors in the treatment of many tumor types in hundreds of clinical trials, which patients will have a response and/or clinically benefit from mTOR inhibition remains unclear." (PMID 19778445, 2009). "The prognostic relevance of p-mTOR and p-Akt expression was assessed using a multivariate proportional-hazards model adjusted for established clinical prognostic factors (i.e., depth of tumour invasion, lymph node involvement, histological type, sex, and age)." (PMID 19223902, 2009). "Importantly, these effects were downregulated both by hypoxia and by HIF-1α, whose stabilization obtained with either CoCl2 or by using proteasome inhibitor (Z-LLF) was preventing BMP2 induced Akt/mTOR activation, especially in tumor cells." (PMID 19587783, 2009). "Similarly, decreases of the proliferation marker Ki-67 in tumour samples have been correlated with mTOR inhibitor activity." (PMID 19436299, 2009). "This study aimed to test whether [18F]fluoro-D-glucose (FDG) uptake of tumours measured by positron emission tomography (PET) can be used as surrogate marker to define the optimal biological dose (OBD) of mTOR inhibitors in vivo." (PMID 19436299, 2009). "Particularly, simultaneous blocking of EGF and VEGF receptor activation combined with Akt-mTOR inhibition may profoundly increase the magnitude and duration of anti-tumor effects exerted by single agent application." (PMID 19473483, 2009). "In this study, we have set out to test whether quantitative changes in tumour FDG uptake qualify as a surrogate endpoint for predicting the dose-dependent antitumour activity of the mTOR inhibitor everolimus." (PMID 19436299, 2009). "For example, data have shown that rapamycin and everolimus can enhance the anti-tumour activity of paclitaxel in a manner related in occurrence and extent to the tumour, dose, and interestingly, the sequence of administration of the mTOR inhibitor and paclitaxel." (PMID 19127256, 2009). "Since NVP-BEZ235 had effects in inhibiting mTOR, and at low doses could reduce tumor development in this model, we treated a cohort of ENU-treated Tsc2+- mice with NVP-BEZ235 at full dosage, 45 mg/kg PO QD, and compared outcome with RAD001 treatment." (PMID 19527517, 2009). "However, the combined inhibition of EGFR, Akt, and mTOR after EGCG+tamoxifen treatment provides a powerful suppression of tumour growth." (PMID 18797454, 2008). "Collectively, these data demonstrate that patients who had tumours that coexpressed caveolin-1 and an activated AKT/mTOR pathway have significantly shorter recurrence-free survival than those patients who had tumours that expressed caveolin-1 alone or activated AKT/mTOR components alone." (PMID 18283322, 2008). "It is known that inhibition of mTOR pathway correlates with decreasing of angiogenesis: in fact, rapamycin is able to reduce tumour vascularisation by promoting endothelial cell death and inducing increased susceptibility of tumour-specific vessels to thrombosis." (PMID 18319715, 2008). "Host-related factors (i.e. vasculature) might impede tumour cell drug delivery thereby impairing effective mTOR inhibition and the anti-proliferative response." (PMID 22275966, 2008).
tumor (continued). "In addition, the dominant mechanism for tumour suppression is the concomitant decrease in tumour protein expressions of mTOR and the EGFR." (PMID 18797454, 2008). "Evaluation of the expression status of both caveolin-1 and mTOR pathway components in these tumours may help predict tumour response to novel pathway-specific therapies, hence allowing appropriate selection of treatment for individual patients." (PMID 18283322, 2008). "As mTOR is a major regulator of protein translation and other processes important in cell proliferation, this protein as well as its targets, S6K and 4EBP1 were also examined in tumour extracts." (PMID 18797454, 2008). "However, for these studies we have utilized the DNA-damaging agent cisplatin, given the available data on sensitization of tumor cells to this agent with p21 attenuation by the mTOR inhibitors and other agents." (PMID 17300726, 2007). "We set out to test the hypothesis that PPARγ ligands activate tuberous sclerosis complex-2 (TSC2), a tumor suppressor gene that inhibits mTOR signaling." (PMID 17597835, 2007). "Furthermore, a substantial body of preclinical studies suggest that tumours with persistent Akt activation have heightened responses to inhibition of the mammalian target of rapamycin (mTOR)." (PMID 17342092, 2007). "Potentially, the ratio of 4E-BP to eIF4E may determine whether inhibition of mTOR elicits a biologically significant tumour response." (PMID 16953237, 2006). "It will be important to determine whether mTOR activation is heterogeneous or activated in only certain subsets of tumours and whether in vivo phospho-AKT is affected by these treatments." (PMID 15956968, 2005). "The first is that mTOR activity could be confined to areas of growth or invasion that would have been missed by our examination of bulk tumour protein." (PMID 15956968, 2005). "Interestingly, phospho-RPS6 was markedly reduced in tumours, suggesting that mTOR activity was lower than observed in cell lines." (PMID 15956968, 2005). "GPNMB reactivity is non‐specific and cannot distinguish between FLCN‐mutated tumours and TFE3/TFEB RCCs, as well as various other TSC1/2/MTOR‐mutated tumours, but it may be diagnostically useful for screening for FLCN mutations that would help distinguish them from their mimics." (PMID 41384711, 2026). "Furthermore, MTF may reduce the Insulin/IGF‐1 levels, thereby inactivating its downstream PI3K/Akt/mTOR signaling pathways to inhibit tumor cell proliferation." (PMID 41456173, 2026). "Similarly, fluphenazine is effective against melanoma, triple-negative breast cancer, and colon cancer, inducing mitochondrial apoptosis, cell cycle arrest, and disruption of the PI3K/AKT/mTOR pathways, thereby reducing tumor growth and enhancing immune responses." (PMID 40718442, 2025). "Some studies suggest that excessive BCAAs supplementation may promote the growth of certain tumor cells by activating the mTOR signaling pathway, thus requiring cautious use in liver cancer patients, especially with individualized adjustments based on the patient’s condition and nutritional needs." (PMID 40438606, 2025). "The PI3K/mechanistic target of rapamycin kinase (mTOR) signaling pathway is also affected by genetic mutations in both NF1 and NF2, with its aberrant activation driving cell growth, proliferation, and survival, thereby playing a pivotal role in tumor development." (PMID 41359105, 2025). "Additionally, considering the potential anti‐tumor effects of Rapamycin (mTOR inhibitor), we evaluated the combinational inhibitory effects of CFI‐402257 and Rapamycin on the proliferation of TCL cells, and found that the combined treatment with Rapamycin enhanced anti‐TCL effect of CFI‐402257." (PMID 39836493, 2025).